ZSCAN5DP (zinc finger and SCAN domain containing 5D pseudogene)
Synonyms: ZSCAN5D; ZNF495D
Gene: Unprocessed pseudogene on chromosome 19 (56,244,043 to 56,247,482, forward strand). Ensembl gene ENSG00000267908.
Subcellular location: Nucleus
Diseases named in the same sentence as ZSCAN5DP in open-access papers:
ZSCAN5DP is named in the same sentence as 1 disease in open-access papers, as found by Europe PMC text mining. Sharing a sentence is not in itself a finding about the gene and the disease.
ZSCAN5DP shares sentences with these, for which no sentence is quoted: infection (2 papers).